PCSK9 (proprotein convertase subtilisin/kexin type 9)
Diseases named in the same sentence as PCSK9 in open-access papers (continued):
Sharing a sentence is not in itself a finding about the gene and the disease.
liver cancer (continued). "To verify the promotion of PCSK9 on tumor growth in vivo, we established liver orthotopic human liver cancer xenograft model in BALB/c nude mice and obtained a consistent conclusion." (PMID 33789749, 2021). "From the regulatory roles of PRDM1, S100A proteins, and PCSK9 to the implications of FoxO1 and CSF-1R, these results pave the way for novel therapeutic approaches aimed at modulating TAMs and enhancing immune responses in liver cancer." (PMID 40764998, 2025). "PCSK9 inhibition disrupted the p62/Keap1/Nrf2 antioxidant axis, effectively disrupting tumor metabolism, inducing metabolic exhaustion, and increasing cancer cell vulnerability to iron‐induced lipid peroxidation, thus suggesting that anti‐PCSK9 therapy is an effective treatment for liver cancer." (PMID 40145543, 2025). "PCSK9 inhibitors may enhance the efficacy of cancer treatment, although their function in liver cancer remains unresolved." (PMID 38275613, 2024). "Therefore, anti-PCSK9 treatment of liver cancer cells leads to a reduction in their aggressiveness during tumor development." (PMID 36612001, 2022). "Interestingly, in a very recent study, PS was shown to inhibit the expression and secretion of PCSK9 in hepatic cancer cells, HepG2 and Huh7, respectively." (PMID 36552895, 2022). "Hence, according to the analysis of public databases and our own assessment, PCSK9 expression is higher in liver cancer tissues and cells." (PMID 36611859, 2022). "Nonetheless, the present results suggest that inhibition/silencing PCSK9 could potentially be considered as a promising anti-cancer approach to treat liver cancers." (PMID 36552895, 2022). "Anti-PCSK9 alone or in combination with statin treatment can live up to this challenge and disrupt the process of oncogenesis opening up new avenues for potential drug repositioning for the treatment of liver cancer." (PMID 36612001, 2022). "This feature may further support the anti-tumoral effect of targeting PCSK9 in liver cancer cells." (PMID 36612001, 2022). "At the same time, since PCSK9 is involved in the degradation of several cell surface lipoprotein receptors, higher levels of this enzyme could reflect a possible slowdown of lipoprotein uptake by liver cancer cells." (PMID 36612001, 2022). "The inhibitors of PCSK9 reduce serum LDL-c levels and show a correlation with the occurrence and progression of liver cancer." (PMID 37746259, 2023). "Our study investigated the relationship between liver cancer and the effects of inhibit HMGCR and PCSK9, respectively." (PMID 37746259, 2023). "The present study aimed to assess the interest of inhibiting PCSK9 and HMGCR in liver cancer using different in vitro and in vivo experimental approaches." (PMID 36612001, 2022). "Our initial observation of defective expression of many enzymes and factors involved in lipid metabolism in liver cancers such as SREBP2 transcription factor led us to focus on its main targets, PCSK9 and HMGCR." (PMID 36612001, 2022). "We confirmed the same tendencies for SREBF2, PCSK9 and HMGCR expression in three liver cancer cell lines (e.g., HepG2, Huh6 and Huh7) in comparison with the normal liver cell line THLE2." (PMID 36612001, 2022). "Therefore, we showed that inhibiting either enzymes PCSK9 or HMGCR, in which expression increases in liver cancer, was effective in reducing tumoral cell growth." (PMID 36612001, 2022). "While still little is known on the role of PCSK9 in HBV, PCSK9 expression is suppressed in HCC tissues, and use of PCSK9-inhibitory antibodies may thus contribute to the development of liver cancers." (PMID 35162992, 2022). "Therefore, it was not inconceivable to expect the alteration of lipid homeostasis we have observed in liver cancer cells in the absence of PCSK9; lipid receptors madly play when PCSK9 is away." (PMID 36611859, 2022).
liver cancer (continued). "Interestingly, unlike the absence of clinical use of anti-PCSK9 alone, this approach here was sufficient to reverse many oncogenic functions of liver cancer cells, e.g., cell proliferation, migration and aggressiveness." (PMID 36612001, 2022).
prostate carcinoma (17 papers, 2021 to 2026). A carcinoma that arises from epithelial cells of the prostate gland. "Secondly, we conducted various sensitivity analyses to further investigate the finding between genetically proxied PCSK9 inhibition and prostate cancer risk." (PMID 36595504, 2023). "Thirdly, using genetic instruments at the PCSK9 locus extracted from a GWAS of LDL-c, liver-derived PCSK9 expression, and circulating PCSK9 protein, this work focuses on the indirect association between PCSK9 inhibition and prostate cancer risk." (PMID 36595504, 2023). "In summary, our study demonstrates that genetically proxied inhibition of PCSK9 is strongly associated with a lower risk of overall and early-onset prostate cancer, potentially through a mechanism involving the lowering of Lp(a) levels." (PMID 36595504, 2023). "Genetically proxied inhibition of PCSK9 was strongly associated with a lower risk of developing prostate cancer (IVW MR odds ratio (OR) = 0.85, 95% confidence interval (95% CI) = 0.76 to 0.96, P = 0.009, per standard deviation (SD) reduction in LDL-c)." (PMID 36595504, 2023). "This mitigates the likelihood that individual pleiotropic variants at the PCSK9 locus are influencing prostate cancer risk via alternate biological pathways." (PMID 36595504, 2023). "Follow-up analyses of genetically proxied PCSK9 inhibition highlighted a potential mediatory role for Lp(a) along the causal pathway to lower prostate cancer risk." (PMID 36595504, 2023). "Genetic correlation results identified evidence for correlation between LDL-c and prostate cancer risk at the PCSK9 loci (correlation coefficient rho = 1)." (PMID 36595504, 2023). "This study provided evidence of an association between genetically proxied PCSK9 inhibition and lower risk of overall and early-onset prostate cancer supported by both MR and colocalization approaches." (PMID 36595504, 2023). "The putative causal relationship between PCSK9 inhibition, Lp(a), and prostate cancer risk is illustrated in a directed acyclic graph." (PMID 36595504, 2023). "Additional LocusZoom plots visualising genetic variants associated with LDL-c and prostate cancer at PCSK9, HMGCR, and NPC1L1 genes provided similar results." (PMID 36595504, 2023). "A LocusZoom plot comparing the cis-acting eQTLs associated with liver tissue-derived PCSK9 expression and SNPs associated with risk of prostate cancer identified a shared top SNP (rs553741) in the PCSK9 gene region." (PMID 36595504, 2023). "In contrast, few preclinical studies have linked PCSK9 to prostate cancer, although Gan and colleagues previously demonstrated that PCSK9 siRNA protects human prostate cancer cells from ionising radiation-induced cell damage." (PMID 36595504, 2023). "For prostate cancer, significant associations were observed for genetically proxied PCSK9 inhibition and low odds of prostate cancer (OR: 0.81; 95% CI 0.71–0.92; P = 0.002)." (PMID 35151363, 2022). "Genetically proxied PCSK9 inhibition was associated with a reduced risk of prostate cancer (OR: 0.81; 95% CI 0.73–0.90; P = 4.52 × 10–5)." (PMID 35151363, 2022). "PCSK9 inhibition appeared to be implicated in prostate cancer by regulating the expression of squalene monooxygenase and lectin-like oxidized low-density lipoprotein receptor-1." (PMID 35151363, 2022). "In the sensitivity analysis applying the weighted median method, the association of genetically proxied PCSK9 inhibition with prostate cancer (OR: 0.85; 95% CI 0.76–0.95; P = 0.005) remained significant." (PMID 35151363, 2022). "However, analyses using cis-pQTL derived from liver tissue would be valuable to further examine the effect of PCSK9 inhibition on prostate cancer risk once these data are available in sufficient samples." (PMID 36595504, 2023).
prostate carcinoma (continued). "Furthermore, genetically proxied PCSK9 exhibited the strongest magnitude of association with the risk of early-onset prostate cancer than that of overall prostate cancer, and there is weak evidence for association with advanced disease." (PMID 36595504, 2023). "Further research is required to investigate the consequences of this approach towards prostate cancer risk, although our findings using genetic proxies of PCSK9 inhibition predict that this would have a beneficial effect, especially on early-onset prostate cancer." (PMID 36595504, 2023). "PCSK9 inhibition may be involved in biological mechanisms that reduce the risk of overall and early-onset prostate cancer, potentially through the regulation of Lp(a)." (PMID 36595504, 2023). "Analysis on disease subtypes provided similar magnitude of association with genetically proxied PCSK9, although confidence intervals overlapped the null (early-onset prostate cancer: OR = 0.91, 95% CI = 0.91 to 1.03, P = 0.139; advanced prostate cancer: OR = 0.93, 95% CI = 0.86 to 1.01, P = 0.102)." (PMID 36595504, 2023). "Although our findings suggest that Lp(a) may play a mediatory role along the pathway between PCSK9 inhibition and prostate cancer risk, further functional work is required to robustly demonstrate this." (PMID 36595504, 2023). "In this work, we have identified strong evidence using large-scale genetic data to suggest that therapeutic inhibition of lipid-lowering drug target PCSK9 may reduce prostate cancer risk." (PMID 36595504, 2023). "MR estimates were supportive of an association between lower levels of PCSK9 gene expression (instrumented using the eQTL) and a lower risk of overall prostate cancer (OR = 0.90, 95% CI = 0.86 to 0.95, P = 5.50 × 10−5, per SD reduction in PCSK9 transcript levels)." (PMID 36595504, 2023). "Similarly, leveraging large-scale summary-level data from PRACTICAL meant that we were unable to evaluate the time-varying effects of PCSK9 inhibition on risk of prostate cancer at separate stages in the life course or in population subgroups undergoing different treatment regimens." (PMID 36595504, 2023). "PCSK9 and PSA levels appear to be inversely correlated in the entire study cohort, gathering men at risk and men with prostate cancer." (PMID 39888285, 2025). "Two sample Mendelian randomization analyses were used to investigate the association of genetically proxied targets (PCSK9, HMGCR, and NPC1L1) with the risk of onset of prostate cancer." (PMID 38398019, 2024). "Several drugs targeting lipid metabolism have been developed for the treatment of prostate cancer, including statins, proprotein convertase subtilisin/kexin type 9 (PCSK9) inhibitors, and sterol regulatory element-binding protein (SREBP) inhibitors." (PMID 39351232, 2024). "It has been shown that PCSK9 siRNA treatment protects prostate cancer cells exposed to radiation by reducing apoptosis and MMP inhibition." (PMID 38398019, 2024). "Further evidence from clinical studies on prostate cancer incidence and progression among patients taking PCSK9 inhibitors is needed to confirm this finding." (PMID 36595504, 2023). "We firstly applied drug target MR to investigate the association of genetically proxied lipid-lowering drug targets (HMGCR, PCSK9, and NPC1L1) with overall prostate cancer risk." (PMID 36595504, 2023). "MR analyses provided a similar central effect estimate for genetically proxied HMGCR estimates and prostate cancer as those found for PCSK9 inhibition, although with wider corresponding confidence intervals resulting in weaker evidence of an effect." (PMID 36595504, 2023). "Genetically proxied inhibition of HMGCR provided evidence of a similar magnitude of effect on overall prostate cancer as PCSK9, although the 95% CI included the null (OR = 0.83, 95% CI = 0.62 to 1.13, P = 0.244)." (PMID 36595504, 2023).
prostate carcinoma (continued). "Future studies with prostate derived PCSK9 cis-pQTL are essential for evaluating the direct role of PCSK9 in prostate cancer cells, especially the effect on advanced prostate cancer." (PMID 36595504, 2023). "On the other hand, silencing PCSK9 by siRNA reduces radiation-induced apoptosis in prostate cancer cell lines, PC-3 and LnCap and thus enhances cell viability." (PMID 34782856, 2021). "Research indicates that inhibition of PCSK9 can protect prostate cancer cells from radiation-induced cell damage, suggesting that PCSK9 may be a promising therapeutic target for enhancing radiosensitivity in prostate cancer." (PMID 38617549, 2024). "In another recent meta-analysis, patients with PCSK9 loss of function mutation have a lower odds of prostate cancer compared to non-mutant PCSK9 subjects." (PMID 36900189, 2023). "For example, leave-one-out analyses found consistent effect estimates for genetically proxied PCSK9 on prostate cancer risk, suggesting the association is unlikely to be driven by any single variant in our instrument." (PMID 36595504, 2023). "Taken together, these findings suggest that the genetically proxied association between PCSK9 inhibition and a lower risk of prostate cancer is unlikely to be due to a mechanism involving the lowering of LDL-c levels." (PMID 36595504, 2023). "Leave-one-out analyses provided consistent evidence of an association between genetically proxied PCSK9 inhibition and risk of prostate cancer, suggesting that the overall estimate was not driven by a single influential variant." (PMID 36595504, 2023). "In prostate cancer, PCSK9 was found to be an inducer for PC progression and recurrence." (PMID 37103355, 2023). "Leave-one-out sensitivity analysis showed that the association between PCSK9 inhibition and prostate cancer was not substantially driven by any individual SNP." (PMID 35151363, 2022). "PCSK9 could be used as a therapeutic target for prostate cancer." (PMID 39736777, 2024). "To assess whether the effects of statins on prostate cancer are due to HMGCR inhibition specifically or merely a consequence of lipid-lowering, we also performed Mendelian randomization analyses using genetic variants associated with other statin drug targets (PCSK9)." (PMID 41601954, 2026). "The aim of this study was to examine the association between genetically proxied inhibition of lipid-lowering drug targets (i.e., PCSK9, NPC1L1, HMGCR) and prostate cancer using evidence from multiple datasets and analytical methods." (PMID 36595504, 2023). "In the main analysis of prostate cancer, fixed-effect IVW models were used for HMG-CoA reductase and NPC1L1 because of no heterogeneity, while random effect IVW model was also used for PCSK9." (PMID 35151363, 2022). "In contrast, genetically proxied inhibition of PCSK9 (OR: 0.81; 95% CI 0.73–0.90; P < 0.001) but not HMG-CoA reductase and NPC1L1 was negatively associated with prostate cancer." (PMID 35151363, 2022).
thrombosis (17 papers, 2014 to 2025). "Studies in mice revealed lower risk for venous thrombosis in individuals with PCSK9 deficiency in comparison with wild-type ones (the presence of inferior vena cava thrombosis: 25% vs. 60%, p < 0.05)." (PMID 41002634, 2025). "In summary, deficiency in PCSK9 is associated with protection against venous thrombosis by reducing leukocyte recruitment and NET formation at the site of thrombosis." (PMID 39767636, 2024). "Similar findings regarding cardiovascular risk were obtained for PCSK9, which was shown to induce thrombosis and hypercoagulability." (PMID 35566668, 2022). "In man, hints in favor of the involvement of PCSK9 in coagulation come from the greater susceptibility to venous thrombosis among individuals with high anti-phospholipid antibodies titers in the presence of nucleotide polymorphisms of the PCSK9 gene." (PMID 34884442, 2021). "The purpose of the current study was to determine the effect of PCSK9 on development of venous thrombosis using a model of genetic PCSK9 deficiency." (PMID 29084995, 2017). "In addition, Existing research has discovered that PCSK9 deficiency has been associated with a reduced risk of venous thrombosis, potentially mediated through decreased leukocyte recruitment and attenuated formation of NETs at the site of thrombus development." (PMID 41462858, 2025). "Furthermore, compared to WT mice, PCSK9-deficient mice exhibited a reduced incidence of venous thrombosis following ligation of the inferior vena cava, as well as decreased neutrophil extracellular trap (NET) formation and leukocyte attachment." (PMID 39767636, 2024). "As expected, PCSK9 deficiency improves the outcome of venous thrombosis." (PMID 33364976, 2020). "In conclusion, deficiency of PCSK9 is associated with protection from venous thrombosis." (PMID 29084995, 2017). "Compared with the baseline, PCSK9i decreased serum LDL-c, ox LDL, thrombosis, alkane (Tx) B2, sNOX2-dp and PCSK9 levels (p < 0.001)." (PMID 36230934, 2022). "For example, PCSK9 knockout mice develop less arterial thrombosis and show reduced in vivo platelet activation upon arterial injury." (PMID 35596184, 2022). "PCSK9 and platelets: Thrombosis strictly depends on the adhesion, activation and aggregation of platelets." (PMID 34070931, 2021). "Since NET formation has been shown by several groups to promote venous thrombosis, it is likely that by affecting myeloid cell recruitment following IVC stasis, PCSK9 deficiency leads to reduced subsequent NET formation." (PMID 29084995, 2017). "Since in this model the leucocyte recruitment was associated with an increased CXCL1 (a chemoattractant that enhanced NETosis) expression and was P-selectin dependent, the myeloid cell recruitment is proposed as a possible mechanism by which PCSK9 enhances NETosis induced thrombosis." (PMID 35323669, 2022). "Thus, transgenic PCSK9+/+ murine models showed a systemic hypercoagulable environment reflected by elevated circulating thrombin/antithrombin complexes while PCSK9−/− mice developed less venous thrombosis after inferior vena cava ligation as compared with wild strains." (PMID 34884442, 2021).